TMEM106B (transmembrane protein 106B)
Description:
In neurons, involved in the transport of late endosomes/lysosomes. May be involved in dendrite morphogenesis and maintenance by regulating lysosomal trafficking. May act as a molecular brake for retrograde transport of late endosomes/lysosomes, possibly via its interaction with MAP6 (By similarity). In motoneurons, may mediate the axonal transport of lysosomes and axonal sorting at the initial segment (By similarity). It remains unclear whether TMEM106B affects the transport of moving lysosomes in the anterograde or retrograde direction in neurites and whether it is important in the sorting of lysosomes in axons or in dendrites (By similarity). In neurons, may also play a role in the regulation of lysosomal size and responsiveness to stress. Required for proper lysosomal acidification (By similarity). (Microbial infection) Plays a role in human coronavirus SARS-CoV-2 infection, but not in common cold coronaviruses HCoV-229E and HCoV-OC43 infections. Involved in ACE2-independent SARS-CoV-2 cell entry. Required for post-endocytic stage of virus entry, facilitates spike-mediated membrane fusion. Virus attachment and endocytosis can also be mediated by other cell surface receptors.
Synonyms: MGC33727; FLJ11273; HLD16
Tractability: Antibody: UniProt places it where antibodies can reach, with high confidence; UniProt predicts a signal peptide or a membrane-spanning region; its Gene Ontology location is reachable by antibodies, with medium confidence. PROTAC: ubiquitination databases record sites on it; its protein half-life has been measured.
Gene: Protein-coding gene on chromosome 7 (12,211,042 to 12,243,367, forward strand). Ensembl gene ENSG00000106460.
Subcellular location: Late endosome membrane; Lysosome membrane; Cell membrane
Subcellular location (Human Protein Atlas): Endosomes; Lysosomes
Gene Ontology:
Molecular function: ATPase binding; protein binding
Biological process: dendrite morphogenesis; lysosome localization; lysosomal transport; lysosome organization
Cellular component: endosome; late endosome membrane; lysosomal membrane; lysosome; plasma membrane
Genetic constraint (gnomAD): Loss-of-function variants: 11 observed, 22.39 expected, observed/expected ratio (o/e) 0.49, 90% interval 0.31 to 0.81. The upper end of that interval is the gene's LOEUF score, 0.81, which puts it in group 3 of 6, group 1 being the genes least tolerant of losing a copy. Missense variants: 241 observed, 285.83 expected, observed/expected ratio (o/e) 0.84, 90% interval 0.76 to 0.94. Synonymous variants: 116 observed, 103.44 expected, observed/expected ratio (o/e) 1.12, 90% interval 0.96 to 1.31.
Gene-disease validity (ClinGen):
ClinGen rates the evidence that TMEM106B causes each of these diseases.
leukodystrophy, hypomyelinating, 16 (autosomal dominant): Definitive.
Homologues: Orthologues: macaque TMEM106B (99% identical), pig TMEM106B (98% identical), rabbit TMEM106B (97% identical), dog TMEM106B (96% identical), guinea pig TMEM106B (96% identical), mouse Tmem106b (96% identical), chimpanzee TMEM106B (95% identical), zebrafish tmem106bb (72% identical), rat Tmem106b (70% identical), tropical clawed frog tmem106b (69% identical).
Diseases named in the same sentence as TMEM106B in open-access papers:
TMEM106B is named in the same sentence as 76 diseases in open-access papers, as found by Europe PMC text mining. Sharing a sentence is not in itself a finding about the gene and the disease. The quoted sentences say what the papers report.
frontotemporal lobar degeneration (57 papers, 2014 to 2026). "Genetic variation in the lysosomal and transmembrane protein 106B (TMEM106B) modifies risk for several neurodegenerative disorders, especially frontotemporal lobar degeneration (FTLD)." (PMID 39711302, 2025). "Transmembrane protein 106B (TMEM106B) encodes a lysosomal membrane protein and was identified as a risk factor for frontotemporal lobar degeneration (FTLD)." (PMID 39044012, 2025). "TMEM106B variants that increase TMEM106B expression levels are linked to several neurodegenerative diseases, including frontotemporal lobar degeneration (FTLD)." (PMID 40451428, 2025). "The endolysosomal proteins progranulin and TMEM106B were both initially associated with frontotemporal lobar degeneration but have subsequently also been linked to other neurodegenerative diseases." (PMID 40713630, 2025). "In 2010, an international collaboration identified three SNPs in TMEM106B as the main susceptibility loci for frontotemporal lobar degeneration with TAR DNA binding protein (TDP-43) inclusions (FTLD-TDP)." (PMID 38674351, 2024). "TMEM106B is known to be a risk factor for frontotemporal lobar degeneration and has been recently identified as the receptor needed for the entry of SARS-CoV-2, independently of angiotensin-converting enzyme 2 (ACE2)." (PMID 39194695, 2024). "TMEM106B was firstly identified as a risk factor for developing frontotemporal lobar degeneration with TDP-43 inclusions (FTLD-TDP) through a genome-wide association study in 2010." (PMID 39872397, 2024). "Beneficial effects of reduced TMEM106B levels have been reported, especially in frontotemporal dementia-related phenotypes in progranulin-deficient mice where the loss of TMEM106B ameliorated abnormal lysosomal phenotypes." (PMID 37443768, 2023). "Firstly, in GWASs of clinical frontotemporal dementia, TMEM106B variants achieved only modest p-values and odds ratios for the behavioral subtype of frontotemporal dementia, and the associations were dependent on GRN mutations." (PMID 37131074, 2023). "The increase in TMEM106B levels with ageing was specific to carriers of the rs1990622-A allele in the TMEM106B gene that increases risk for frontotemporal dementia, Alzheimer’s disease, Parkinson’s disease, and hippocampal sclerosis with ageing." (PMID 37726834, 2023). "Genetic variants in TMEM106B are a common risk factor for frontotemporal lobar degeneration and the most important modifier of disease risk in patients with progranulin (GRN) mutations (FTLD-GRN)." (PMID 36707901, 2023). "Mutations of TMEM106B have been identified as genetic risk factors for neurodegenerative diseases including Frontotemporal lobar degeneration (FTLD) and limbic-predominant age-related TAR DNA binding protein 43 (TDP-43) encephalopathy." (PMID 37563705, 2023). "Genetic variants in TMEM106B are a common risk factor for frontotemporal lobar degeneration (FTLD) and the most important modifier of disease risk in patients with progranulin (GRN) mutations (FTLD-GRN) identified as early as 2010." (PMID 36707901, 2023). "Tmem106b is associated with frontotemporal dementia (FTD), but recent GWAS studies also demonstrated its association with AD." (PMID 37174641, 2023). "The lysosomal protein TMEM106B was identified as a risk modifier of multiple dementias including frontotemporal dementia and Alzheimer’s disease." (PMID 37901434, 2023). "TMEM106B, a type II lysosomal transmembrane protein, has recently been associated with brain aging, hypomyelinating leukodystrophy, frontotemporal lobar degeneration (FTLD) and several other brain disorders." (PMID 35287730, 2022). "Genetic variants in transmembrane protein 106 B (TMEM106B) are genetic modifiers of frontotemporal lobar degeneration with TDP-43 pathology (FTLD-TDP) in patients with pathological G4C2 hexanucleotide expansions in C9orf72." (PMID 36619668, 2022).
frontotemporal lobar degeneration (continued). "The transmembrane protein 106B (TMEM106B) gene is a susceptibility factor and disease modifier of frontotemporal dementia, but few studies have investigated its role in amyotrophic lateral sclerosis." (PMID 36012536, 2022). "Genetic variation at the TMEM106B locus has been identified as a risk factor for frontotemporal lobar degeneration with TDP-43 inclusions (FTLD-TDP), especially for individuals with granulin (GRN) gene mutations." (PMID 35344985, 2022). "TMEM106B has also been implicated in frontotemporal dementia in humans, which has been recently recognized as a disease with a common pathogenic background with ALS." (PMID 36142395, 2022). "Genetic variants in TMEM106B have been associated with frontotemporal lobar degeneration with TDP-43 pathology and disease progression in C9ALS/FTD." (PMID 36619668, 2022). "In 2010, a common TMEM106B genetic variant rs1990622 (T>C) was first identified to be associated with frontotemporal dementia (FTD) risk (OR = 1.64 for T allele, allele frequency = 0.679, and P = 1.08E−11)." (PMID 33461566, 2021). "This is in line with results from a study in mice which showed that loss of TMEM106B function rescued lysosomal phenotypes related to frontotemporal dementia." (PMID 32492070, 2020). "TMEM106B associated with frontotemporal dementia (FTD) and PD is involved in lysosomal trafficking and function." (PMID 32106459, 2020). "The TMEM106B locus has been implicated in cognitive aging, with functional consequences in frontotemporal dementia related to lysosomal activity." (PMID 32492070, 2020). "Strikingly, both impaired trafficking and the increased dendritic branching were rescued by treatment with antisense oligonucleotides targeting the well validated frontotemporal dementia risk factor TMEM106B, which encodes an endolysosomal protein." (PMID 30496365, 2018). "TMEM106B has been identified as a risk factor for ﻿frontotemporal lobar degeneration ﻿with progranulin mutations and elevated mRNA and protein levels of TMEM106B are associated with increased risk for frontotemporal lobar degeneration." (PMID 28126008, 2017). "Literature data have widely proven that TMEM106B variants are genetically associated to frontotemporal lobar degeneration–TDP-43 pathology and are considered a major risk factor for this disease." (PMID 28460069, 2017). "Together, these results indicate that brain atrophy in presymptomatic carriers of common frontotemporal dementia mutations is affected by both genetic and environmental factors such that TMEM106B enhances the benefit of cognitive reserve on brain structure." (PMID 28460069, 2017). "Transmembrane protein 106B (TMEM106B) has been identified as a risk factor for frontotemporal lobar degeneration, which is the second most common form of progressive dementia in people under 65 years of age." (PMID 26651479, 2015). "A large genome-wide association study (GWAS) attempting to identify risk factors for frontotemporal lobar degeneration (FTLD) with TDP43 inclusions uncovered TMEM106B, a protein with unknown function at the time." (PMID 40451428, 2025). "Transmembrane protein 106B (TMEM106B) was first linked to neurodegenerative diseases, when sequence variations in its gene were identified as a risk factor for frontotemporal lobar degeneration with TDP-43 inclusions (FTLD-TDP), especially in individuals with granulin gene (GRN) mutations." (PMID 38886865, 2024). "The increase in TMEM106B levels with age was specific to carriers of the rs1990622-A allele in the TMEM106B gene that is associated with increased risk for frontotemporal dementia, Alzheimer's disease, Parkinson's disease, and hippocampal sclerosis with ageing." (PMID 36711721, 2023). "TMEM106B, a gene encoding a type II transmembrane protein of unknown function, was initially identified as a risk factor for frontotemporal lobar degeneration (FTLD) with GRN mutations." (PMID 35287730, 2022).
frontotemporal lobar degeneration (continued). "Although TMEM106B has been associated with frontotemporal dementias and other diseases, the evidence for a causal relationship between TMEM106B aggregation and disease remains unclear, and distinct TMEM106B folds do not characterize different diseases." (PMID 35344985, 2022). "Single nucleotide polymorphisms (SNPs) inherited as one of two common haplotypes at the transmembrane protein 106B (TMEM106B) locus are associated with the risk of multiple neurodegenerative diseases, including frontotemporal lobar degeneration with pathological inclusions of TDP-43." (PMID 29970152, 2018). "Notably, TMEM106B was repeatedly identified as a risk gene for frontotemporal lobar degeneration." (PMID 34859065, 2021). "We identified two genes (UNC5C and ENC1) with converging evidence from all three analytic steps, and also showed that a previously reported risk gene for frontotemporal lobar degeneration, TMEM106B, might play a role in the dissociation of cognition and neuropathology in older adults." (PMID 28441426, 2017). "Variants in TMEM106B are associated with increased neuroinflammation in aging, frontotemporal lobar degeneration (FTLD)-TDP, and with AD and our prior study suggested a protective role of the TMEM106B variant rs3173615 in CTE." (PMID 36895005, 2023). "Since the initial identification of TMEM106B as a risk factor for frontotemporal lobar degeneration (FTLD), multiple genetic studies have found TMEM106B variants to modulate disease risk in a variety of brain disorders and healthy aging." (PMID 36056242, 2022). "TMEM106B [P SKAT.corr < 1.00E-03 and Pburden.test.corr = 0.0177, ORburden.test = 0.56 and CI95%.burden.test = (0.38, 0.82)] was associated with frontotemporal dementia." (PMID 30863397, 2019). "This indicates that reducing TMEM106B levels can restore endosomal health in frontotemporal dementia." (PMID 30496365, 2018). "The TMEM106B genotype has also been found to be a modifier of the age at disease onset in frontotemporal dementia patients with TDP-43 pathology." (PMID 28460069, 2017). "In summary, our mouse model nicely recapitulates the interaction between progranulin and TMEM106B in human patients and supports a critical role of lysosomal dysfunction in the frontotemporal lobar degeneration﻿ (FTLD) disease progression." (PMID 28126008, 2017). "Transmembrane protein 106B (TMEM106B), previously identified as a risk factor in frontotemporal lobar degeneration, has recently been detected to form fibrillar aggregates in the brains of patients with various neurodegenerative diseases (NDs) and normal elders." (PMID 39872397, 2024). "TMEM106B is known to be involved in frontotemporal lobar degeneration, a neurodegenerative disease." (PMID 36848389, 2023). "Transmembrane protein 106B (TMEM106B) is a lysosomal transmembrane protein associated with lysosome trafficking and activity in motor neurons and dendritic cells and is the cause of frontotemporal dementia in patients with large deletions." (PMID 34834963, 2021). "However, how progranulin and TMEM106B interact to regulate lysosomal function and frontotemporal lobar degeneration﻿ (FTLD) disease progression is still unclear." (PMID 28126008, 2017). "In this study, we aimed to investigate the modifying effects of TMEM106B in the largest collection of patients with systematically ascertained FTD and families from the ARTFL/LEFFTDS Longitudinal Frontotemporal Lobar Degeneration (ALLFTD) study, on gray matter volume and cognitive measures." (PMID 39321401, 2024). "Two of the novel AD loci (TMEM106B, GRN) are also known frontotemporal dementia (FTD) genes, suggesting their potential roles in protein clearance rather than in specific disease-related protein aggregates." (PMID 34935119, 2022).
frontotemporal lobar degeneration (continued). "The TMEM106B and GRN signals in frontotemporal lobar degeneration with TAR DNA-binding protein (TDP-43) inclusions (frontotemporal lobar degeneration TDP) probably share causal variants with ADD (coloc PP4 = 99.8% and coloc PP4 = 80.1%, respectively)." (PMID 35379992, 2022). "TMEM106B has been identified as a genetic modifier in FTD, modulating the age at disease onset in frontotemporal lobar degeneration–TDP-43 disease." (PMID 28460069, 2017). "To mimic elevated levels of TMEM106B in frontotemporal lobar degeneration﻿ (FTLD) cases, we generated transgenic mice expressing TMEM106B under the neuronal specific promoter, CamKII." (PMID 28126008, 2017).
Alzheimer disease (27 papers, 2014 to 2026). A progressive, neurodegenerative disease characterized by loss of function and death of nerve cells in several areas of the brain leading to loss of cognitive function such as memory and language. "This is intriguing, as previous reports indicate that the TMEM106B rs1990622-A variant that is associated with increased risk for Alzheimer’s disease is also correlated with higher levels of the TMEM106B protein in the hippocampus." (PMID 39606446, 2024). "A TMEM106B variant was shown to confer protection in the inflammatory late-onset Alzheimer’s disease in another study." (PMID 37146150, 2023). "TMEM106B is also implicated in pathological presentation of Alzheimer’s disease and lysosomal dysfunction has been shown to be implicated in Alzheimer’s disease as well." (PMID 28126008, 2017). "Therefore, it is possible that TMEM106B might have more general effects on neurodegenerative diseases associated with defects of the endolysosomal pathway, such as Alzheimer’s disease and Parkinson’s disease, than previously believed." (PMID 26651479, 2015). "We dissect distributional regulatory effects at established Alzheimer’s Disease (AD) risk genes including PITRM1, TMEM106B, and the CHRNE/SCIMP/RABEP1 cluster, revealing complex context-dependent regulatory architecture missed by linear analysis." (PMID 41377971, 2025). "Our initial findings showed a strong correlation between TMEM106B genetic variants and APOE mRNA levels, which suggest an involvement in Alzheimer’s disease." (PMID 38674351, 2024). "Findings from ENC1, UNC5C, and TMEM106B converged to suggest a possible role in determining cognitive resilience in the aging population affected by Alzheimer's disease, stroke and other NDs." (PMID 39351424, 2024). "In Alzheimer’s disease, TMEM106B protein levels increased shortly after the emergence of cognitive impairment." (PMID 38674351, 2024). "In human temporal cortices, the mean TMEM106B expression was significantly higher in Alzheimer’s disease compared to cognitively unimpaired individuals." (PMID 38674351, 2024). "For example ENC1, UNC5C, and TMEM106B have been suggested as determinants of cognitive resilience in the aging population affected by Alzheimer's disease, stroke and other neuropathologies." (PMID 39351424, 2024). "TMEM106B is not only a genetic risk factor for ALS and FTD but is also implicated in other neurodegenerative diseases such as Alzheimer’s disease." (PMID 39606446, 2024). "Elevated levels of TMEM106B in mild cognitive impairment, Alzheimer’s disease and during hippocampal reinnervation in rodents all point to an active response to tissue damage that is consistent with compensatory synaptic and terminal remodeling." (PMID 38674351, 2024). "TMEM106B variants were additionally found to associate with the presence of TDP-43 pathology in other diseases, such as Alzheimer’s disease and hippocampal sclerosis." (PMID 29855382, 2018). "Recent studies indicate that TMEM106B plays a pathological role in various neurodegenerative diseases, including Alzheimer’s disease (AD)." (PMID 24684749, 2014). "At Alzheimer’s disease (AD) risk loci, qQTL analysis revealed complex regulatory architecture including variance effects at PITRM1, lower-quantile-specific effects at TMEM106B partially explained by APOE ε4 interactions, and coordinated epigenetic regulation at loci harboring CHRNE/SCIMP/RABEP1." (PMID 41377971, 2025). "Furthermore, TDP-43 inclusions are also present in Alzheimer disease and Parkinson disease, explaining the broader modifying roles of TMEM106B in endophenotypes such as cognition across neurodegenerative diseases." (PMID 39321401, 2024). "Similarly, we find a relationship at the cellular level between TMEM106B pathology and phosphorylated Tau burden in Alzheimer’s disease." (PMID 39606446, 2024). "The goal of this study is to determine whether TMEM106B is mis-regulated in Alzheimer’s disease or in other neurodegenerative conditions." (PMID 38674351, 2024).